GLP1R (glucagon like peptide 1 receptor)
Diseases named in the same sentence as GLP1R in open-access papers (continued):
Sharing a sentence is not in itself a finding about the gene and the disease.
diabetes (continued). "Enantioselective synthesis revealedoral efficacy for (S)-9 in animal models.Compound 9 behavior bolsters the interest of a small-moleculePAM of GLP-1R as a promising therapeutic approach for the increasinglyprevalent obesity-associated diabetes." (PMID 35349261, 2022). "Diabetes is a known risk factor in glaucoma, and GLP-1R agonists’ wide usage in diabetes treatment presents an opportunity to retrospectively evaluate its effects among patients with coexisting glaucoma in a large-scale observational study." (PMID 33147455, 2020). "Given its glycemic efficacy and ability to reduce the body weight, glucagon-like peptide 1 receptor (GLP-1R) agonism has emerged as a preferred treatment for diabetes associated with obesity." (PMID 33349332, 2020). "Glucagon-like peptide 1 receptor agonists (GLP1RAs) have been incorporated by the European Association for the Study of Diabetes as a safe treatment." (PMID 31814880, 2019). "Glucagon-like peptide-1 receptor (GLP-1R) agonists are used to treat diabetes and promote weight loss." (PMID 31767019, 2019). "Nutritionally and chemical induced diabetes were chosen in order to elucidate the mechanism(s) associated with GLP-1R expression in T1DM and T2DM." (PMID 25893200, 2015). "Furthermore, the beneficial effect of GLP-1R agonist treatment in a preclinical model of diabetes was partially attenuated in JNK3-deficient mice." (PMID 41480766, 2026). "Glucagon-like peptide-1 receptor agonists (GLP-1RAs) have significantly advanced the treatment of diabetes and obesity along with their associated cardiometabolic complications since their initial approval by the U.S. Food and Drug Administration (FDA) in 2005." (PMID 41376649, 2026). "Furthermore, there appears to be growing evidence that glucagon-like peptide 1 receptor agonists are associated with a reduced risk of obesity-related cancers, with particular evidence where diabetes and obesity are concurrent." (PMID 39941422, 2025). "Furthermore, in diabetes, chronic hyperglycemia has been associated with reduced GLP-1R expression in pancreatic β-cells, resulting in reduced insulin secretion." (PMID 40076236, 2025). "For example, the inclusion of GIPR targets in GLP-1R/GCGR agonists may buffer the risk of diabetes from chronic GCG receptor excitation." (PMID 40004115, 2025). "Perioperative pulmonary aspiration is a critical complication linked to significant morbidity and mortality, particularly in high-risk populations such as patients with diabetes, obesity, gastroparesis, or those using Glucagon-Like-Peptide-1 receptor agonists (GLP-1 RAs)." (PMID 39663603, 2024). "In conclusion, individuals with diabetes face a heightened risk of ischemic stroke, and treatment with GLP-1R agonists may potentially provide stroke-related benefits." (PMID 39148946, 2024). "Glucagon-like peptide-1 receptor agonists rank among the most effective medications for lowering blood glucose and body weight, as well as reducing cardiovascular risk in individuals with diabetes." (PMID 38982987, 2024). "Acute OXM infusion improves glucose tolerance in T2DM patients making dual agonists of the glucagon receptors and GLP-1R new promising treatments for diabetes and obesity with the potential for weight loss and glucose lowering superior to that of GLP-1R agonists." (PMID 37234809, 2023). "Multiplex PCR combined with resequencing Hi-Reseq technology was used to detect single nucleotide polymorphisms of the glucagon-like peptide-1 receptor gene, and the allele frequency, genotype distribution, and clinical parameters were analyzed between each diabetes subgroup and the control group." (PMID 38131033, 2023). "GLP-1R agonist use is also associated with a reduced risk for glaucoma in patients with diabetes." (PMID 37362000, 2023).
diabetes (continued). "As retinal vascular abnormalities are prevalent comorbidities of DR, and GLP-1R analogs have already been used clinically in diabetes and obesity, further pre- and clinical research is necessary to elucidate the regulative mechanism underlying GLP-1R/SGLT2 signaling in DR." (PMID 36465606, 2022). "Furthermore, in this model, diabetes duration was found independently and negatively associated with GLP-1R mRNA expression (P=0.028)." (PMID 36465606, 2022). "Our study focused on alleviating microglia-mediated neuroinflammation in depression, which might help in the clinical application of GLP-1R agonists in the treatment of depression associated with diabetes." (PMID 36615696, 2022). "More recently the clinical use of GLP-1R agonist based therapeutics at high doses for the treatment of obesity and diabetes has resulted in weight loss in the 9–16% range over 26–68 weeks depending on diabetes status and the degree of lifestyle intervention." (PMID 35461369, 2022). "It is supposed that GLP-1R agonists may be a promising therapy in depression associated with diabetes." (PMID 36615696, 2022). "The Glucagon-Like Peptide-1 receptor (GLP-1R) agonists, which are already approved for the treatment of diabetes and obesity due to their weight loss-inducing effect, have recently been investigated to improve NAFLD in animals and humans, yielding promising results." (PMID 36289914, 2022). "In addition, because of very high cardiovascular risk, CAD patients with diabetes mellitus should receive a sodium-glucose co-transporter 2 inhibitors or a glucagon-like peptide-1 receptor agonist." (PMID 35401229, 2022). "Two different mice strains were used (C57BL/6 Wild Type and C57BL/6 Akita mice; i.e., mice developing diabetes due to an insulin 2 gene mutation), and in both groups, there were animals with normal expression of GLP1R and animals with GLP1R deficiency (GLP1R−/−)." (PMID 34639160, 2021). "Trial evidence indicates that glucagon-like peptide-1 receptor agonists (GLP-1 RAs) may reduce the risk of cardiovascular (CV) events in patients with diabetes and myocardial infarction (MI)." (PMID 31999317, 2021). "Furthermore, a role for endogenous GLP-1 in the development of diabetes-associated bone fragility has been identified, with GLP-1R KO mice presenting with reduced bone mass through increased osteoclast activity." (PMID 34093449, 2021). "We assessed weight course in a real-life diabetes secondary care setting and analyzed its association with patient characteristics, lifestyle habits and initiation of insulin, glucagon like peptide-1 receptor agonists (GLP-1 RA) and sodium-glucose co-transporter-2 inhibitors (SGLT-2i)." (PMID 31216324, 2019). "Given that GLP-1R agonists are associated with not only successful weight loss but also glycaemic control, the Endocrine Society has suggested that they can be used as a first-line agent or an add on to other therapies for patients with diabetes." (PMID 25894803, 2015). "Furthermore, all three GLP-1R agonists have been shown to assist people with T2D in achieving the recommended American Diabetes Association target HbA1c goal of <53 mmol/mol (<7%)." (PMID 22776039, 2013). "Additionally, the effectiveness of GLP-1R agonist treatments for weight loss in people with diabetes may be impacted by their potential difficulties in maintaining exercise routines compared to those without diabetes." (PMID 38440786, 2024). "Therefore, we hypothesized that GLP-1R agonist has a regulatory function in diabetes-associated VC for insufficient mitophagy in VSMCs." (PMID 38720283, 2024). "Also, GLP-1R agonists can protect the heart and kidneys, reduce the risk of cardiovascular events, and delay the progress of diabetic nephropathy, which is especially important for people with diabetes." (PMID 36843578, 2023).
diabetes (continued). "Among these, tirzepatide, a long-acting dual GLP-1R/GIPR agonist approved for diabetes and obesity, shows enhanced therapeutic outcomes on cardiometabolic diseases compared to selective GLP-1R agonists." (PMID 41506148, 2026). "Glucagon-like peptide-1 receptor agonists (GLP-1 RAs) are increasingly prescribed for patients with diabetes, obesity, and cardiometabolic disease." (PMID 41776829, 2026). "Rationale: The emergence of glucagon-like peptide-1 receptor agonists (GLP-1RAs) has advanced diabetes management." (PMID 41356183, 2026). "Seven percent were treated with oral antidiabetes medications or glucagon-like peptide-1 receptor agonists at diabetes diagnosis, increasing to 15.3% at follow-up." (PMID 41958866, 2026). "Tirzepatide is a glucagon-like peptide-1 receptor (GLP-1R) agonist and glucose-dependent insulinotropic polypeptide receptor (GIPR) agonist that is used for diabetes mellitus and weight loss." (PMID 42226819, 2026). "Glucagon-like peptide-1 receptor agonists (GLP-1RAs) have emerged as effective therapies for diabetes mellitus and obesity." (PMID 41376649, 2026). "Recent advances have further introduced multi-receptor incretin agonists for diabetes and obesity treatment, with GLP-1R agonism serving as a central component." (PMID 41506148, 2026). "GLP-1R agonists have been explored as therapeutic strategies to increase and/or preserve β cell mass in diabetes, aiming to maintain functional β cells and induce their survival and regeneration." (PMID 41480766, 2026). "Among the most important changes in diabetes management in the last generation is the dramatic clinical benefits produced by select glucagon-like peptide-1 receptor agonists (GLP-1 RA) and sodium glucose cotransporter-2 (SGLT2) inhibitors." (PMID 40119283, 2025). "This case underscores the importance of recognizing EDKA, particularly in the context of rising glucagon-like peptide 1 receptor agonist use for diabetes and weight management." (PMID 40026933, 2025). "Studies with glucagon-like-peptide 1 receptor agonists for the treatment of diabetes, obesity, or chronic kidney disease." (PMID 41375628, 2025). "In conclusion, the activation and promising application of GLP-1R offer broad possibilities for the future treatment of diabetes and related diseases." (PMID 40520185, 2025). "In summary, the importance of GLP-1R in the field of diabetes treatment is not only reflected in its precise regulation of blood glucose, but also in its ability to comprehensively manage multiple complications." (PMID 40520185, 2025). "We searched Scopus, PubMed/MEDLINE, and Google Scholar for articles without time restriction, using combinations of the following key words: “ferroptosis”, “pyroptosis”, “diabetes mellitus” and “glucagon-like peptide-1 receptor agonists”." (PMID 41244507, 2025). "We also highlight the power of our approach by interrogating the internalization behaviour of GIPR and GLP1R, two main targets in the treatment of diabetes and obesity." (PMID 39610654, 2025). "Glucagon-like peptide-1 receptor (GLP-1) agonists are approved for clinical use to treat diabetes and obesity." (PMID 39535805, 2025). "Glucagon-like peptide-1 Receptor (GLP1R) agonists have become extensive anti-obesity/diabetes medications in the United States." (PMID 39865816, 2025). "Spurred by the enormous therapeutic success of glucagon-like peptide-1 receptor (GLP-1R) agonists (GLP1-RAs) against diabetes and obesity, glucagon family receptor pharmacology has garnered a tremendous amount of interest." (PMID 40806371, 2025). "Glucagon-like peptide-1 receptor (GLP-1R) agonists, such as the peptide-based drug semaglutide, have emerged as cornerstone therapies in the management of diabetes." (PMID 41373699, 2025). "Glucagon-like peptide-1 receptor agonist (GLP-1 RA) is a class of incretin-based therapies widely used in the management of type 2 diabetes mellitus (T2DM)." (PMID 41502515, 2025).
diabetes (continued). "Glucagon-like peptide-1 receptor agonists are already widely used for obesity and diabetes, including increasing self-administration by patients outside medical supervision." (PMID 40972535, 2025). "In recent years, GLP-1R and its agonists have become a hot research topic and a star drug in the field of diabetes treatment." (PMID 40520185, 2025). "GLP-1R activation has been extensively studied for its dual role in managing diabetes-related complications and reducing cardiac hypertrophy." (PMID 39861172, 2025). "Glucagon-like peptide-1 receptor agonists (GLP-1RAs) are novel drugs approved for diabetes and obesity." (PMID 42239616, 2025). "Given its functions, GLP-1R and its agonists hold significant therapeutic potential in the treatment of many diseases related to metabolism, such as diabetes." (PMID 40564143, 2025). "While both are coupled to the Gs pathway, GLP-1R is in parallel also coupled to Gq signaling, an attribute potentially contributing its preserved insulinotropic effectiveness under conditions of diabetes." (PMID 40024571, 2025). "It is also possible that the larger improvement in individuals with prediabetes or diabetes is the result of the increasing use of glucagon-like peptide-1 receptor agonists (GLP-1RA), which are more frequently prescribed in these individuals." (PMID 40599337, 2025). "The in silico studies focused on molecular docking analyses targeting key proteins relevant to diabetes treatment, such as the glucagon-like peptide-1 receptor (GLP-1R) and the insulin receptor (IR)." (PMID 41155553, 2025). "The glucagon-like peptide-1 receptor (GLP-1R) is a key target for diabetes mellitus (DM) treatment, and GLP-1R agonists are pharmaceutical compounds employed in the treatment of DM." (PMID 40778306, 2025). "As glucagon-like peptide-1 receptor agonists (GLP-1RAs) become first-line therapies for diabetes and obesity, their safety in patients with premalignant pancreatic lesions remains uncertain." (PMID 41153613, 2025). "Conclusions: 1,25-D3 alleviates neuroinflammation and improves vascular endothelial dysfunction through multitarget and multipathway by upregulating the GLP-1R/PI3K/AKT signaling axis to improve diabetes-induced brain injury." (PMID 40224490, 2025). "AMTs have attracted attention for delivering GLP-1 and GLP-1R agonists in metabolic diseases, such as obesity and diabetes." (PMID 41471111, 2025). "Glucagon-like peptide-1 receptor agonists (GLP-1 RAs) play a pivotal role in diabetes management by stimulating the production of glucagon-like peptide-1." (PMID 41041641, 2025). "While GCGR/GLP-1R dual agonists like cotadutide and survodutide have advanced into clinical studies, the investigative focus remains largely on diabetes, obesity, and liver fibrosis." (PMID 41280890, 2025). "The diabetes therapeutic landscape has been dominated in past years by glucagon-like peptide-1 receptor agonists (GLP-1 RA) and SGLT2i, medications that have demonstrated multiple metabolic, cardiovascular, renal, and possible neurological benefits." (PMID 40806701, 2025). "Glucagon-like peptide-1 receptor agonists (GLP-1 RAs) represent a cornerstone in the treatment of diabetes and obesity and have emerged as a promising option for other metabolic disorders, including hepatic steatosis." (PMID 40735319, 2025). "In recent years, Glucagon-like peptide-1 receptor (GLP-1R) and its agonists have attracted much attention in the field of diabetes treatment." (PMID 40520185, 2025). "In our study, we tested protein imprinting and PCR to detect the mRNA and protein levels of GLP-1R in the cerebral cortex of diabetes rats." (PMID 40224490, 2025). "Clinical studies have shown that GLP-1R reduces ROS levels, the mitochondrial membrane potential and mitochondrial apoptosis in patients with diabetes, as well as alleviating levels of OS and attenuating low-grade inflammation." (PMID 40778306, 2025).
diabetes (continued). "This systematic review aimed to evaluate the cardiovascular effectiveness and safety of initiating sodium-glucose cotransporter 2 inhibitors (SGLT2i) in comparison to glucagon-like peptide 1 receptor agonists (GLP-1RA) among elderly patients with diabetes." (PMID 40933374, 2025). "Nowadays, incretin mimetic drugs such as glucagon-like peptide 1 receptor (GLP-1R) agonists have gained extensive popularity for the treatment of diabetes and obesity." (PMID 41312422, 2025). "A major advancement in diabetes treatment was achievedwith the development of glucagon-like peptide-1 receptor agonists(GLP-1RAs)." (PMID 40698392, 2025). "For example, GLP-1R/GIPR dual agonists have demonstrated superior glucose-lowering and weight-loss effects in the treatment of diabetes and obesity." (PMID 40520185, 2025). "Novel agents such as finerenone provide cardiorenal benefits in patients with diabetes and chronic kidney disease, while glucagon-like peptide-1 receptor agonists show promise in preserved or mildly reduced ejection fraction, particularly with obesity." (PMID 41156123, 2025). "Nevertheless, the research and development of GLP-1R agonists provide new perspectives and strategies for the treatment of diabetes, obesity, and related complications." (PMID 40520185, 2025). "Our findings offer novel insights into the design of small-molecule GLP-1R agonists and provide a promising lead for the development of improved therapeutic agents for diabetes management." (PMID 41373699, 2025). "Here we report that tirzepatide (TZP), a novel polypeptide/glucagon‐like peptide 1 receptor (GIPR/GLP‐1R) agonist for the treatment of diabetes, has a role in attenuating CRC growth." (PMID 40125821, 2025). "In recent years, the mechanism of action and therapeutic applications of GLP-1R have received extensive attention, especially in the field of diabetes and obesity treatment." (PMID 40520185, 2025). "The glucagon-like peptide-1 receptor (GLP-1R) has emerged as a focus of interest in both diabetes and oncology research." (PMID 40361517, 2025). "Core search terms included the following: “GLP-1 receptor agonist”, “glucagon-like peptide-1 receptor agonist”, “semaglutide”, “liraglutide”, “obesity”, and “diabetes” or “diabetic”." (PMID 41341350, 2025). "Glucagon-like peptide-1 receptor (GLP1R) agonists have gained attention for their role in diabetes treatment along with their diverse effects, such as appetite suppression, suggesting potential psychiatric benefits." (PMID 40770700, 2025). "Glucagon-Like Peptide-1 Receptor (GLP1R) agonists have become widespread anti-obesity/diabetes pharmaceuticals in the United States." (PMID 39865816, 2025). "The purpose of this paper is to assess the effect of glucagon-like peptide-1 receptor agonists (GLP-1RAs) on stroke or heart disease in patients having chronic respiratory disease and diabetes (CD) with underlying diseases related to COVID-19." (PMID 38540106, 2024). "Patients with liver steatosis and diabetes mellitus can benefit from medications like glucagon-like peptide 1 receptor agonists or sodium-glucose co-transporter 2 inhibitors, as far as both hyperglycemia and fatty liver are concerned." (PMID 38465109, 2024). "Overall, our data demonstrated that the glucometabolic improvement effect of baicalein on diabetes was largely attenuated with Glp1r KO." (PMID 39456499, 2024). "In summary, finerenone normalizes Glp1r and Gcgr that are downregulated in the kidneys of mice with comorbid diabetes, likely through its anti-fibrotic effects on neighbouring cells." (PMID 39582036, 2024). "Chronic GLP1R activation inhibited IL-1β expression in the myocardium of rats with streptozotocin-induced diabetes." (PMID 38732142, 2024). "Glucagon-like peptide-1 receptor agonists (GLP-1-RAs) are a novel class of medications promising for treating type 2 diabetes mellitus (T2DM) and obesity-related conditions such as cardiovascular disease (CVD) and non-alcoholic fatty liver disease (NAFLD)." (PMID 39355484, 2024).